HNF4A (hepatocyte nuclear factor 4 alpha)
Diseases named in the same sentence as HNF4A in open-access papers (continued):
Sharing a sentence is not in itself a finding about the gene and the disease.
hepatocellular carcinoma (continued). "HNF4γ2 is an isomer of HNF4α, which can restore dedifferentiated hepatoma cells to a more differentiated state by promoting the expression of hepatocyte markers." (PMID 35096588, 2021). "Enhanced activities from preS1, preS2/S, core promoter, and Enh- II as a result of binding of liver enriched TFs, including HNF1α, HNF3α and HNF4α were observed using hepatoma cells." (PMID 33810128, 2021). "These in vivo data support the conclusion from in vitro cell models that upregulation of lnc‐APUE, resulting from HNF4α downregulation, promotes hepatoma growth by upregulating the E2F1 level." (PMID 33854885, 2021). "First, we determined the expression level of HNF4α using transient as well as stable HBV expression human hepatoma cell lines." (PMID 32023898, 2020). "HNF4α has been shown to control iron homeostasis in liver and hepatoma cells through the regulation of transferrin, transferrin receptor-1 and hepcidin genes." (PMID 31532389, 2019). "Epigenetic modification promotes growth arrest and up-regulates the expression of the hepatic key regulator gene HNF4α in various hepatoma cells which induces increased CYP expression and Albumin production." (PMID 30654452, 2019). "To understand the mechanisms of trilobatin inducing the proliferation of HepG2 cells, we determined the expression of HBXIP and HNF4α, which had been reported to affect the growth of both normal liver cells and hepatoma cells in vitro." (PMID 31540429, 2019). "HNF4α, a member of the nuclear receptor family of transcription factors, could maintain hepatocyte differentiation in the adult healthy liver, and its loss may directly contribute to hepatocellular carcinoma development (Bonzo, Ferry, Matsubara, Kim, & Gonzalez, 2012)." (PMID 30916358, 2019). "Overexpression of HNF4α in hMSCs suppressed hepatocellular carcinoma development through downregulation of the Wnt/β-catenin signaling pathway." (PMID 29921325, 2018). "In contrast, knockdown of PGC-1α and HNF-4α by RNA interference in hepatoma cells reversed HBV activation in response to cisplatin." (PMID 29472690, 2018). "Here we report that the human FBP1 gene is regulated by two liver-enriched transcription factors, CCAAT-enhancer binding protein-α (C/EBPα) and hepatocyte nuclear factor 4α (HNF4α) in human hepatoma HepG2 cells." (PMID 29566023, 2018). "In contrast, an additional isoform of HNF4α, driven by an alternative promoter (P2-HNF4α), is induced in HNF4α-positive human hepatocellular carcinoma (HCC)." (PMID 30341289, 2018). "This enhancement promoted hepatoma cells progressing into invasive cell by the attenuation of HNF4α, which is essential for liver development and hepatocyte function." (PMID 29983862, 2018). "Hepatic expression and/or activity of HNF4α are decreased markedly in severe cirrhotic livers, alcoholic liver disease, tumor necrosis factor-α-induced hepatotoxicity, and hepatoma progression." (PMID 29234104, 2017). "HNF4α mutants account for maturity-onset diabetes of young people, and its deletion promotes the formation of hepatic carcinoma." (PMID 26870992, 2016). "We found that reduced expression of Exo70 and HNF4α was important for berberine-induced G2/M cell cycle arrest in hepatoma cells, suggesting their potential roles in cell cycle regulation." (PMID 26848864, 2016). "Recently, conflicting reports have defined HNF4α as both tumor promoter and tumor suppressor in hepatocellular carcinoma (HCC)." (PMID 26848864, 2016). "Together, our results identify Exo70 as a novel transcriptional target of HNF4α to promote cell cycle progression in hepatoma, thus provide a basis for the development of therapeutic strategies for hepatocellular carcinoma." (PMID 26848864, 2016). "A previous study from our laboratory reported that HNF4α re-established the expression profile of characteristic hepatocyte markers in hepatoma cells." (PMID 27050273, 2016).
hepatocellular carcinoma (continued). "In the present study, we accidently found that berberine reduced the expression of HNF4α and Exo70, which is critical for its effect on G2/M transition of hepatoma cells." (PMID 26848864, 2016). "Results showed that knocking down either HNF4α or Exo70 arrested human hepatoma cell cycle at G2/M phase." (PMID 26848864, 2016). "Recent findings suggest an inhibitory effect by HNF4α on hepatic carcinoma progression, which was attributed to inhibition of the Wnt/β-catenin signaling pathway." (PMID 26870992, 2016). "Cell cycle analysis further revealed that down-regulation of HNF4α and Exo70 was essential to berberine-stimulated G2/M cell cycle arrest in hepatoma cells." (PMID 26848864, 2016). "In this study, we found Exo70 expression in human hepatoma cells was greatly reduced after knocking down hepatic nuclear factor 4α (HNF4α), the most important and abundant transcription factor in liver." (PMID 26848864, 2016). "Moreover, in hepatitis B virus (HBV)-associated hepatocellular carcinoma (HCC), hepatocyte nuclear factor 4α (Hnf4α) was found to activate miR-122 gene transcription." (PMID 27322213, 2016). "In the present study, we provide evidences that HNF4α transcriptionally regulates Exo70 gene expression in human hepatoma cells through binding to the HNF4α-response element (HRE) within the Exo70 promoter, which contributes to the G2/M cell cycle transition." (PMID 26848864, 2016). "It has also been shown that HNF4α plays a role in the inflammation processes of the liver and hepatocellular carcinoma by regulating the transcription of miR-122." (PMID 26657215, 2015). "In a gene expression profiling studies with primary human hepatocytes and human hepatoma cell lines a Matrigel sandwich configuration retained abundant expression of LETFs such as CEBPα and HNF4α." (PMID 25901575, 2015). "Together, HBx inhibits human CYP2E1 gene expression via downregulating HNF4α which contributes to promotion of human hepatoma cell growth." (PMID 25238230, 2014). "Both HNF4α and c-Myc proteins compete for control of the P21/CDKN1A gene transcription, and deletion of HNF4A in hepatocellular carcinoma cells results in significant up-regulation of c-Myc and enhanced cell proliferation rates." (PMID 25050814, 2014). "To examine this more closely, we performed co-silencing experiments of TCF7L2 and HNF4α, and examined the expression of several metabolic genes in the hepatoma cells." (PMID 25414334, 2014). "We found that ectopic overexpression of HBx inhibits CYP2E1 gene expression via downregulating HNF4α in cultured HepG2 cells and promotes hepatoma cell growth." (PMID 25238230, 2014). "Consistent with the mRNA data above, Tcf7l2 silencing led to an increase in HNF4α protein levels 24 and 48 h after electroporation in hepatoma cells." (PMID 25414334, 2014). "For the first time, we demonstrate that the balance between TCF7L2 and HNF4α levels determines the expression of numerous metabolic genes in hepatoma cells." (PMID 25414334, 2014). "We previously illustrated that in hepatoma Huh7 cells HNF4α facilitated SHP shuttling from the mitochondria to the nucleus." (PMID 23874642, 2013). "To investigate HNF4α binding to Alu repeats in the promoters of HNF4α target genes in vivo, we performed a ChIP assay for HNF4α in human hepatocellular carcinoma HepG2 cells that express HNF4α and many of its target genes." (PMID 22085832, 2011). "A functional role of HNF4α in apoptosis seems to be a β-cell restricted effect, as overexpression of HNF4α in hepatoma cells, embryonic F9 cells as well as in HEK293 cells exclusively affects cell proliferation." (PMID 19835622, 2009). "HNF4α is a key transcription factor involved in liver development, metabolic regulation, and pancreatic β-cell function, but its dysregulation is implicated in the progression of several cancers, notably hepatocellular carcinoma (HCC) and pancreatic ductal adenocarcinoma (PDAC)." (PMID 40926269, 2025).
hepatocellular carcinoma (continued). "Likewise, injection of mesenchymal stem cells expressing HNF4A in orthotopic human hepatomas in athymic, nude mice results in smaller tumors and decreased metastases through downregulation of Wnt signaling." (PMID 37635981, 2023). "Therefore, mRNA expression of HNF4α in hepatoma cells and PHHs, treated with IL-1ß, was analyzed, and it revealed a significant reduction in HNF4α mRNA expression in Huh7 cells and PHHs." (PMID 37175814, 2023). "However, RNA-Seq data for HNF4A siRNA knockdown (KD) in human hepatoma cell line (Huh7) cells suggested that the HNF4A mediated decrease in the expression of HNF1A and other genes is related to binding activity, the lipid and cholesterol metabolism pathways." (PMID 35327967, 2022). "The genome-wide proximity of YAP/TEAD and HNF4a could also be confirmed in the HEPG2 hepatocellular carcinoma cell line: analysis of the publicly available ChIP-seq data (encode database) showed strong co-localization of TEAD and HNF4a." (PMID 35871292, 2022). "We, therefore, examined whether the suppressed HNF4α by HBx really promotes cell proliferation in human hepatoma cell lines." (PMID 32023898, 2020). "We previously reported a positive correlation between increased H19 expression and HNF4α promoter hypomethylation in human hepatoma cells and in livers of multiple mouse models, including fasting, high fat diet (HFD)-induced T2D, and liver-specific H19 overexpression." (PMID 31953394, 2020). "To explore whether OF anti‐HCC effect is through the ASGR/STAT3/HNF4A pathway, we knockdown the ASGR and HNF4A in Hep3B hepatoma cells, and performed the functional analysis for cell viability assay." (PMID 33377648, 2020). "In this report, we demonstrated that HBV-induced downregulation of HNF4α could enhance the proliferation of hepatoma cells and increase their tumorigenicity both in vitro and in vivo." (PMID 32023898, 2020). "Overexpression of HNF4α was also found to be sufficient in the re-establishment of the hepatocyte marker gene expression, epithelial cell morphology and polarity in dedifferentiated hepatoma cells." (PMID 32365562, 2020). "Knockdown of ASGR1 or HNF4A reverse the OF mediated hepatoma cell proliferation inhibition effect." (PMID 33377648, 2020). "To evaluate whether the downregulation of HNF4α by HBV would affect the tumorigenicity of hepatoma cells in vivo, we investigated the tumor formation and growth in nude mice bearing HepAD38 or HepG2-X xenograft." (PMID 32023898, 2020). "HNF4α can provoke epithelialisation of a dedifferentiated hepatoma cell line (H5)." (PMID 27875772, 2017). "Previous studies showed that HNF4A was dramatically down-regulated or impaired in hepatocellular carcinoma, and that forced expression of HNF4A in hepatocellular carcinoma cells could promote the transition of tumors towards a less invasive phenotype." (PMID 28583088, 2017). "Together, our results identify Exo70 as a novel transcriptional target of HNF4α and contributes to the regulation of cell cycle progression in hepatoma cells, which may provide a suitable target for the development of antitumor strategies." (PMID 26848864, 2016). "In this study, Exo70 was found to be transcriptionally regulated by HNF4α in hepatoma cells." (PMID 26848864, 2016). "Furthermore, forced HNF4α overexpression induced the hepatoma cell differentiation into hepatocytes and suppressed in vivo HCC growth and metastasis." (PMID 27050273, 2016). "As we observe a regulation of Exo70 by HNF4α, we sought to explore whether HNF4α and Exo70 acted in the same axis to regulate hepatoma cell cycle." (PMID 26848864, 2016). "In addition, over-expression of HNF4α induces the differentiation of hepatoma cells into more mature phenotypes, and abolishes the tumorigenesis." (PMID 25965823, 2015).
hepatocellular carcinoma (continued). "The tumor repressive effect is supported by findings that HNF4α inhibits cell proliferation in various cell types, including murine hepatocellular carcinoma cells, endothelial lung and embryonal carcinoma cells, insulinoma cells as well as embryonic kidney cells." (PMID 22140441, 2011). "Thus, re-expression of HNF4α in murine hepatocellular carcinoma (HCC) retarded tumor growth of subcutaneous transplanted cells." (PMID 22140441, 2011). "Moreover, in patients with hepatocellular carcinoma, lower HNF4 α gene expression was observed." (PMID 36012158, 2022). "Correlation coefficient analysis between the expression of HNF4a and top 50 epithelial and mesenchymal genes across liver carcinoma samples demonstrated a strong negative association between the upregulation of HNF4a expression and reduction of mesenchymal-related genes involved in EMT process." (PMID 36132168, 2022). "Incidentally, it has been reported that YAP1 can negatively regulate HNF4α expression through ubiquitination and proteasomal degradation in hepatocellular carcinoma (HCC) cells." (PMID 34693980, 2021). "Therefore, an increase in the PKM1/PKM2 ratio and the activation of hepatocyte nuclear factor 4 alpha (HNF-4α) to induce hepatoma differentiation and suppress cancer progression using oroxylin A could be therapeutically relevant in liver cancer." (PMID 33401572, 2021). "In our other project, we demonstrated Oligo-Fucoidan binds to ASGPR1/2 receptor in normal hepatocyte or hepatoma cells through both in-vitro and in-vivo competition assay, and activate pSTAT3 and bind to the promoter of HNF4a-P1 isoform and increase the expression of Hnf4a (unpublished result)." (PMID 32570707, 2020). "Aberrations in HNF4α functionality are known from the development of severe cirrhotic livers, alcoholic liver disease, tumor necrosis factor-α-induced hepatotoxicity, and hepatocellular carcinoma where HNF4α has an anti-proliferative effect and serves as a tumor suppressor." (PMID 30654452, 2019). "Hence, it is speculated that HBV related IL-23 can enhance malignant properties of hepatoma cells through attenuation of HNF4α." (PMID 29983862, 2018). "In addition, an integrative analysis of NAFLD signatures in human and genetically modified mouse models demonstrated that HNF4A as a transcription factor plays an important role in regulating the expression of the genes involved in the progression of NAFLD to hepatocellular carcinoma." (PMID 29216278, 2017). "Previous studies provided substantial evidence of a striking suppressive effect of hepatocyte nuclear factor 4α (HNF4α) on hepatocellular carcinoma (HCC)." (PMID 27050273, 2016). "Moreover, knocking down either Exo70 or HNF4α induced G2/M phase arrest of hepatoma cells." (PMID 26848864, 2016). "While the expression of albumin and HNF4A remained largely unchanged in HCC-PHHs, PHCs, and HCLs (HepG2 and Huh7), CYP3A4 expression was significantly downregulated in the hepatoma cell lines." (PMID 40862732, 2025). "After 2–3 weeks, these mice developed multifocal liver carcinomas with glandular structures, high KRT19 levels and low HNF4α expression." (PMID 39948437, 2025). "The exogenous expression of HNF4A and FOXA3 in hepatoma cells initiated the endogenous expression of a large number of hepatocyte nuclear factors and promoted the transformation of hepatoma cells into hepatocyte-like cells." (PMID 35132353, 2022). "TNF-α and IFN-γ induced IL-32 in primary human hepatocytes and hepatoma cells that regulate the transcription of HBV core promoter by downregulating HNF1-α and HNF4-α." (PMID 33868257, 2021). "It's worth noting that the combination of three liver transcriptional factors (TF), HNF1A, HNF4A, and FOXA3 transduced the Hepatocellular carcinoma (HCC) cell lines to more stably suppress cell proliferation." (PMID 34234870, 2021). "It has been found that the simultaneous expression of HNF1α, HNF4α and FOXA3 can transform hepatoma cells into hepatocyte-like cells." (PMID 35096588, 2021).
hepatocellular carcinoma (continued). "Moreover, HNF4A upregulation could trigger inhibition of hepatocellular carcinoma proliferation." (PMID 34586697, 2021). "In other studies, researchers have found that the combination of HNF1A, HNF4A and fork head box protein A3 (FOXA3) can reprogram hepatocellular carcinoma cells into hepatocyte-like cells." (PMID 34234870, 2021). "HNF4α was shown to be downregulated in rat primary hepatocyte transfected with HBV plasmid, and in a human hepatoma cell line transfected with HBV plasmid." (PMID 32023898, 2020). "We examined the mRNA expression levels of several hepatocyte/hepatoma markers, such as albumin, ApoA1, CYP3A4, HNF4α, OATP1B3, and AFP in both cell lines and in lung carcinoma-derived A549 cells by qRT-PCR." (PMID 31138826, 2019). "In addition, HBV infection is the main cause of hepatocellular carcinoma (HCC) and drives increased IL-23 production by inducing STAT3 phosphorylation to confine hepatocyte nuclear factor 4 alpha (HNF4α)." (PMID 31443406, 2019). "STAT3 protein together with IL6, HNF4A, HNF1A, and three microRNAs constructed a feedback loop, which regulates oncogenesis of hepatocellular carcinoma (HCC)." (PMID 31219249, 2019). "Hepatocyte nuclear factor 4 alpha (HNF4α), which is essential for liver development and hepatocyte function, was found to be downregulated in HBV integrated or transiently transfected hepatoma cells." (PMID 29983862, 2018). "To examine how prevalent this relationship was, we examined the impact of TRIB1 silencing in another widely studied human hepatoma cell line, HuH-7 cells where TRIB1 suppression led to reduced HNF4A protein." (PMID 28717196, 2017). "Among HCC with Wnt/β-catenin activating mutations, nodules with HNF4α expression can be recognized by EOB-MRI hepatocellular phase, and EOB-MRI can discriminate HNF4α-positive hepatocellular carcinomas with good prognosis with little vascular invasion or distant metastasis." (PMID 39796729, 2024). "Through previous research and our experimental results, KXYA could induce cell apoptosis by increasing the mRNA expression of PTEN and HNF4A, thereby inhibiting the proliferation of HBV related hepatoma cell lines." (PMID 36133813, 2022). "Mechanically, the exogenous expression of HNF1α, HNF4α and FOXA3 in hepatocellular carcinoma cells promotes the endogenous expression of a variety of hepatocyte nuclear factors, including C/EBP, thus promoting the transformation of hepatocellular carcinoma cells into hepatocyte-like cells." (PMID 35096588, 2021). "At the same time, it was also found that the expression of HNF4α could inhibit hepatocyte EMT, and inhibit the formation of hepatoma stem/progenitor cells during carcinogenesis." (PMID 35096588, 2021). "We proved that OF binds to ASGR1/2 receptors on hepatoma cell, we also provided strong evidence that OF activates phosphorylation of STAT3, and then pSTAT3 will bind to P1 promoter of HNF4A, transcriptionally regulates the level of HNF4A, P1 isoform." (PMID 33377648, 2020). "HNF4α and HNF1α expression is lost during liver fibrosis and HCC progression, while their exogenous expression triggers growth arrest in hepatoma cell lines and induces hepatocyte differentiation in dedifferentiated cells." (PMID 31543815, 2019). "In previous work, the mRNA expression of HNF4A was significantly decreased in human NASH samples, suggesting a contribution of HNF4A to NAFLD through regulation of the expression of the genes involved in the progression of NAFLD to hepatocellular carcinoma." (PMID 30200543, 2018). "Interestingly, HNF4G implies a negative regulation by interacting with FOXA1, RXRA, and HNF4A in the human hepatoma cell line and some studies have showed that interrelationships among FOXA1, FOXA2, HNF4A, and HNF4G affect transcriptional regulation." (PMID 29033978, 2017).